HMGB1 (high mobility group box 1)
Diseases named in the same sentence as HMGB1 in open-access papers (continued):
Sharing a sentence is not in itself a finding about the gene and the disease.
cancer (continued). "In this latter context, extensive HMGB1 isoform studies may make it possible to distinguish between the protumorigenic and antitumorigenic activities of this protein and further define its potential role as a prognostic and predictive cancer biomarker." (PMID 32664328, 2020). "Although much has been made of the role of HMGB1 acting as an acute damage associated molecular pattern (DAMP) molecule, prompting the response to tissue damage or injury, it is also released at sites of chronic inflammation including sites of infection, autoimmunity, and cancer." (PMID 31379812, 2019). "In contrast, inhibiting HMGB1 expression (iHMGB1shRNA1 and iHMGB1shRNA2) in feeder cells or activity (EP) attenuated these effects, supporting our hypothesis that HMGB1 released from irradiated cancer cells positively mediates this dedifferentiation process." (PMID 31558702, 2019). "The frequency of mutations and copy number alterations (CNA) in genes encoding HMGB1 and HMGB2 proteins were analyzed as well as in those genes encoding proteins detected in the Y2H search associated with PCa, using the open platform for exploring cancer genomics data, c-Bioportal." (PMID 31694235, 2019). "Thus, contrarily to carboplatin and cisplatin, oxaliplatin might be able to induce an antitumor immune response through its capacity to induce ER stress, CRT exposure, and ATP and HMGB1 release in dying cancer cells." (PMID 31861811, 2019). "Active secretionof HMGB1 occurs from immune cells e.g. macrophages,monocytes, NK cells, while passive secretion occurs fromdamaged necrotic cells.It has extracellular activities as acytokine, since mediates inflammation, proliferation andmigration in different cancers." (PMID 31485132, 2019). "Furthermore, HMGB1-mediated autophagy participates in important cellular processes such as cell fate decisions, chronicity of inflammatory responses and chemosensitivity to cancer-ablative drugs." (PMID 31379812, 2019). "In addition, HMGB1 is activated in CP-resistant cancer cells." (PMID 31311167, 2019). "Expression of HMGB1 protein was observed upregulatedin most of the cancers as shown in generated canceratlas result,confirming that HMGB1protein could be targeted in various types of cancers." (PMID 31485132, 2019). "However, it is unclear whether HMGB1 secreted by dying cancer cells following radiotherapy is involved in expansion of CSCs, especially in the non-CSCs dedifferentiation." (PMID 31558702, 2019). "Finally, such a prophylactic effect was lost when the cancer cells used for vaccination were depleted of CALR or HMGB1, as well as when exposure to 8-MOP plus 4J UVA irradiation was performed in the presence of an ATP-degrading enzyme or a monoclonal antibody blocking type I IFN receptors." (PMID 31371700, 2019). "Although HMGB1 gene SNPs were found not related with risk of cancer based on the findings of our current meta-analysis, some of our included studies indicated that these SNPs could be associated with progression of cancer and overall survival outcomes." (PMID 30049847, 2018). "In addition to the inflammatory effects, HMGB1 plays potential roles in cancer development." (PMID 29853785, 2018). "In addition, HMGB1 has a critical role in cancer metastasis." (PMID 29568761, 2018). "Besides these limitations, our data showed that HMGB1 secreting NB cells could induce Treg differentiation in vitro and thus may serve as a potential therapeutic target in cancer immunotherapy." (PMID 30643519, 2018). "In addition to its nuclear role, HMGB1 could also act as an extracellular signaling molecule to modulate the inflammation, immune response, autophagy and cancer." (PMID 30526602, 2018). "Reduced HMGB1 expression may increase cancer cell sensitivity by limiting autophagy." (PMID 28771183, 2017). "In addition, HMGB1 expression in cancer cells could be increased by a variety of anticancer agents including doxorubicin, cisplatin, methotrexate, docetaxel and gemcitabine." (PMID 29069735, 2017).
cancer (continued). "Furthermore, several HMGB1‐targeting agents have been investigated in experimental cancer models." (PMID 28039939, 2017). "Therefore, the first prerequisite is whether to design a HMGB1 inducer or inhibitor when considering HMGB1 targeted therapeutic, and the targeted treatment of cancer varies at different stages." (PMID 28969092, 2017). "Interestingly, HMGB1 has dual roles in cancer development, progression, and therapy." (PMID 28374746, 2017). "Interestingly, activation of TLR9 with ODN and ODN + HMGB1 showed highly significant proliferation promoting effects in MIAPaCa-2 (155% and 145%, p < 0.0001), BxPC-3 (147% and 133%, p < 0.0001), and PaCaDD135 cancer cells (112% and 118%, p < 0.005)." (PMID 27941651, 2016). "A direct interaction between the two major redox sensors, KEAP1-NRF2 and HMGB1, which are implicated in the onset and progression of cancers related to OS, has not been reported; however they might converge in several signalling pathways." (PMID 26682011, 2016). "The influence of EGCG on the aggregation of HMGB1 could be a route for its anti-cancer efficacy." (PMID 26899177, 2016). "Assuming that HMGB1 is a functionally important cytotoxic compound of the innate immune system, targeting glutaminolysis could enhance the immune system's response against cancer." (PMID 26948869, 2016). "Moreover, it has been reported that Tax1, an oncogenic protein of viral origin, upregulates HMGB1 levels, which suggests that cancers of viral origin could also be related to HMGB1 deregulation." (PMID 26682011, 2016). "Thus, the brisk inhibition of glucose-driven respiration by HMGB1 was best tolerated by cancer cells that could efficiently upregulate glucose fermentation and maintain aerobic respiration by glutamine break-down." (PMID 26948869, 2016). "Furthermore, our results suggest that HMGB1 is actively released by cancer cells under stressful conditions and that this might regulate the proliferation, migration and invasion of myofibroblasts." (PMID 26979829, 2016). "However, it remains inconclusive whether EGCG as an anti-cancer agent is related to the HMGB1 protein." (PMID 26899177, 2016). "Thus, higher concentrations of HMGB1 might also kill anoxic cancer cells that rely solely on anaerobic glycolysis." (PMID 27652323, 2016). "Thus, HMGB1 might be released by cancer cells in areas of low glucose in solid tumours with the resulting activation of myofibroblasts and is a potential therapeutic target to inhibit solid tumour growth." (PMID 26979829, 2016). "HMGB1 is generally located inside the nucleus in normally proliferating cells, and is released to the cytoplasm and even extracellular space following different stimuli, such as starvation, metabolic stress and chemotherapy, in innate immune cells as well as several types of cancer cell lines." (PMID 24996221, 2014). "Therefore we sought to identify whether HMGB1 is overexpressed in cancer tissues compared with normal epithelia tissues." (PMID 24837834, 2014). "Furthermore, survival analysis revealed that HMGB1 overexpression affected cancer-free survival." (PMID 20579387, 2010). "But, HMGB1 may play a controversial role in the occurrence and progression of cancers." (PMID 20579387, 2010). "The serum levels of HMGB1 were increased sequentially according to GC disease stage based on the theory of gastric carcinogenesis and HMGB1 levels were significantly different between normal and high-risk lesions of GC as well as between cancer and non-cancer." (PMID 19476625, 2009).
cancer (continued). "Blocking HMGB1 and its receptor RAGE by using specific inhibitors resulted in similar outcomes, suggesting that the interaction between HMGB1 and RAGE is a crucial driver of cancer progression." (PMID 40277915, 2025). "The High Mobility Group Box 1 (HMGB1) protein, a member of the HMG family, plays a crucial role in both cancer progression and inflammatory responses." (PMID 41354099, 2025). "ICD results in the release of several damage-related molecular patterns (DAMPs), including high mobility group protein 1 (HMGB1), adenosine triphosphate (ATP), and calmodulin (CRT) from cancer cells." (PMID 40291560, 2025). "Elevated circulating HMGB1 and TNF-α levels have been reported in cachectic cancer patients, correlating with skeletal muscle sarcopenia." (PMID 41003013, 2025). "DAMPs that have garnered increasing attention in the cancer research domain in recent years include the S100 protein family, the heat shock protein (HSP) family, and HMGB1." (PMID 41009692, 2025). "Consistently, in cancer cells exposed to immuno-oncologic death ligands such as TRAIL, the PARP1-meidated HMGB1 cytosolic translocation axis maintains autophagic flux to prevent apoptosis, thereby contributing to TRAIL resistance." (PMID 41465435, 2025). "In this study, we found that CCA cell-derived lactate stimulated the dedifferentiation of SCs and significantly induced HMGB1 expression in GFAP+ dSCs, enhancing malignancy of cancer cells." (PMID 40148311, 2025). "Recent studies have revealed that the HMGB1/RAGE axis is intricately involved in cell proliferation, apoptosis, metastasis, autophagy, and angiogenesis in various types of malignant tumors." (PMID 38529373, 2024). "Results showed that the release of adenosine triphosphate (ATP) and high-mobility group box 1 (HMGB1), and the expression level of extracellular calreticulin (CRT) in BLNs-treated cancer cells were significantly higher than those in the control." (PMID 38589867, 2024). "High-mobility group box-1 (HMGB1) is overexpressed in many solid cancers, including CRC, and promotes cancer proliferation, invasion, and metastasis." (PMID 38999957, 2024). "HMGB1 activation also upregulates the release of ICAM-1, VCAM-1, TNF-α, and IL-8, which corresponds to a rise in invasive and metastatic properties of cancer cells." (PMID 39682695, 2024). "In contrast, a few individual genes, such as BAX, CLAR, HMGB1, HSP90A11, IFNA1, and PDIA3, showed weak correlations with the ICD scores in most cancer types." (PMID 38627900, 2024). "In our previous study, we found a notable release of HMGB1 and ANXA1 under low dose of TLC388, prompting ICD and enhancing cancer immunogenicity in vitro and in vivo." (PMID 38564022, 2024). "High mobility group box 1 (HMGB1), a classic ligand of RAGE, has been extensively reported to promote cancer cell progression, particularly in gastrointestinal cancer." (PMID 39068486, 2024). "The present study aimed to examine the relationship between HMGB1, HSP90, S100, ATP, and cytokines in the serum of cancer patients." (PMID 39768997, 2024). "Current studies demonstrate the interplay between HMGB1 and multiple elements in cancer evolution, including BECLIN1, advanced glycation end products RAGE, and PI3K, influencing the advancement of cancer." (PMID 38601753, 2024). "In driving other metastatic cancer progression, HMGB1 activates TLR4 and RAGE signaling, which in turn leads to caspase-1 activation that promotes cancer invasion and metastasis." (PMID 39682695, 2024). "The mouse cachexia model demonstrated high levels of high-mobility group box-1 (HMGB1) and tumor necrosis factor-α (TNFα) in cancer ascites." (PMID 39000167, 2024). "This HMGB1 and RICTOR crosstalk increases PD-L1 generation, promoting the activity of PD-L1 + exosomes in cancer immunotherapy." (PMID 38566199, 2024).
cancer (continued). "When investigating the relationship between immune checkpoint expression and PSME3, we observed that among the 33 cancers, CD276 and CD274 exhibited the highest positive correlation with PSME3, followed by VEGFA, HMGB1, THR4, BTNA2, and ENTDD1." (PMID 38312840, 2024). "In cancer cachexia, inflammatory cytokines such as interleukin (IL)-1, tumor necrosis factor (TNF)-α, IL-6, IL-8, and high-motility group box-1 (HMGB1) promote catabolism through systemic inflammation, resulting in tissue damage." (PMID 39125651, 2024). "Overall, the HMGB1/RAGE axis is involved in the migration, invasion, and metastasis of various cancers." (PMID 38529373, 2024). "The CXCL12/HMGB1 heterocomplex enhances, via CXCR4, the directional migration and invasiveness of cancer cells characterized by high metastatic potential that possess a fully active thioredoxin system, contributing to maintain red-HMGB1." (PMID 38803493, 2024). "Thus, HMGB1 may play an important role in cancer-related myocardial damage." (PMID 39125651, 2024). "This study sheds light on the role of HMGB1 derived from CRC cells in inducing autophagy and apoptosis in cardiomyocytes, thereby contributing to cancer-related myocardial damage." (PMID 38731953, 2024). "RAGE serves as the receptor for HMGB1, and overexpression of RAGE and/or HMGB1 has been documented for various cancers." (PMID 39157201, 2024). "In GSDME-executed pyroptotic cancer cells, pores in the plasma membrane allow DAMP releases, such as ATP, HMGB1, and HSP70." (PMID 38238307, 2024). "High mobility group box 1 (HMGB1) is secreted from activated immune cells, necrotic cells, and certain cancers." (PMID 37759736, 2023). "High-mobility group box 1 (HMGB1) is a versatile protein that plays essential roles in normal cellular processes and pathological conditions, particularly inflammation and cancer." (PMID 37520371, 2023). "TTFields also induce the expression of immunogenic markers on cancer cells, including calreticulin (CRT) on the cell surface and the release of high mobility group box 1 protein (HMGB1), indicating immunogenic cell death." (PMID 37916157, 2023). "High mobility group box 1 (HMGB1) is a transcriptional protein sensitive to oxidative stress and is involved in multiple processes of cancer development, such as cell proliferation, angiogenesis, cell migration, and adhesion." (PMID 37818101, 2023). "We also discovered that HMGB1-mediated CTSL and autophagy-lysosome pathway blockade in cancer cells plays vital roles in the antitumor effects by inhibiting the formation of the Beclin-1-PI3K-III complex." (PMID 37537587, 2023). "It has been observed that a number of NRGs, including DNASE1, HMGB1 and PIK3CA, undergo gains in SCNV across a variety of cancer types, which was consistent with previous studies." (PMID 37408763, 2023). "In IMT, some nanomaterials induce immunogenic death (ICD) of cancer cells, typically by releasing calretin (CRT), high-mobility group protein 1(HMGB1), and adenosine triphosphate (ATP) outside the cell, thereby recruiting immune cells for IMT." (PMID 38069279, 2023). "PTT also induces ICD in cancer cells, typically releasing CRT, HMGB1, and ATP into the extracellular compartment, thereby recruiting immune cells." (PMID 38069279, 2023). "We recently reported that Compound B potently inhibited the HMGB1-stimulated IL-6 production in mouse macrophage-like cells RAW264.7, suggesting dual suppressive actions: anti-inflammatory and anti-cancer activities." (PMID 37505064, 2023). "These viruses have demonstrated their capacity to trigger the release of critical DAMPs, such as ATP, HMGB1, calreticulin, HSP70, and HSP90 from dying cancer cells." (PMID 38077402, 2023). "The ICD cascade events of cancer cells are featured by presenting DAMP molecules, including CRT, ATP, and HMGB1." (PMID 37551065, 2023).
cancer (continued). "Ferroptotic cancer cells released three DAMPs, including HMGB1, ATP, and CRT, promoting immunogenicity that aided in overcoming resistance to the cancer drug." (PMID 37182170, 2023). "It has also been shown that IMQ induces ICD by promoting ROS production, which triggers ER stress followed by surface-exposed CRT, ATP secretion and HMGB1 release, in BCC/KMC-1, AGS, HeLa and B16F10 cancer cells." (PMID 38077402, 2023). "Further comparison of the results revealed that HMGB1 and NCAPG2 were all significantly positively related in pan-cancer, highlighting the necessity to further investigate the mechanisms involved." (PMID 36776838, 2023). "ROS can significantly impact the quantity and quality of non-cancer cells in the vicinity, such as microglia, by modulating redox-responsive transcription factors, including TFEB, Nrf2, HSP72, and HMGB1." (PMID 38132142, 2023). "HMGB1 signaling between esophageal adenocarcinoma cells and macrophages in the vicinity forms an inflammatory TME, which aids cancer progression." (PMID 36982351, 2023). "Prospective studies should include more patients, BC cancer subtypes, NACT regimens and plan, and measurement timepoints to validate the usefulness of these biomarkers, particularly the HMGB1 and E-cadherin combination." (PMID 37684327, 2023). "In this study, we have assessed presentation of three hallmark factors for immunogenic cell death – namely release of HMGB1, secretion of ATP and surface-presentation of CALR – in human cancer cell lines after treatment with radiation and ATR inhibitors." (PMID 37346039, 2023). "It has also been shown that mouse neutrophil-derived NETs trigger HMGB1 release and activate TLR9-dependent pathways in cancer cells to promote their adhesion, proliferation, migration and invasion." (PMID 36788538, 2023). "Metformin has displayed anticancer effects towards different types of cancer cells in an in vitro cell study, with Nrf2, YAP, HIF-1α, HMGB1, TGF-β1, glycolysis and glutamine metabolism being proposed action targets at a cellular level." (PMID 36012397, 2022). "SIRT1 antagonizes macrophage inflammation and cancer induced by chronic inflammation by increasing SIRT1 activator NAD+ and inhibiting HMGB1 release." (PMID 36081910, 2022). "Processes associated with ICD result in the emission of DAMPs, such as HSP70, HSP90, calreticulin, HMGB1, ATP, type I IFN, cancer cell-derived nucleic acids, ANXA1, and others." (PMID 36015189, 2022). "From confocal images, those cancer cells treated with Zn-Fu MNs displayed the significant increase of CRT exposure in cytoplasm and the great decrease of HMGB1 level within nucleus, in comparison to the control group." (PMID 36168615, 2022). "These drugs stimulate cancer cells to release damage-related model molecules, including calreticulin (CRT), adenosine-triphosphate (ATP), high mobility group protein B1 (HMGB1), CXCL1, and CCL2." (PMID 35635307, 2022). "The results show that HMGB1 is highly expressed with a worse OS (overall survival) in KIRC but better OS for ACC and LUAD cancers." (PMID 36230798, 2022). "Similarly, silencing HMGB1 expression could reportedly attenuate the stimulating effects on the migration of irradiated, dying cells, promotion of cancer cell migration via paracrine mechanisms, and enhanced epithelial-mesenchymal transition (EMT) and PI3K/pAkt signaling." (PMID 35812184, 2022). "High mobility group box 1 (HMGB1), a highly conservative nucleoprotein, was a multifunctional protein involved in the regulation of inflammation, cancer and fibrosis progression." (PMID 36699071, 2022). "Mechanistically, during NETosis, neutrophils secrete the high mobility group box 1 (HMGB1) protein, thereby activating TLR9 signaling pathways, which promote cancer cells adhesion, proliferation and migration." (PMID 35158779, 2022). "At the same time, danger signals that include HMGB1 and HSP70 can be secreted/released by damaged cancer cells that boost antitumor immunity." (PMID 35326698, 2022).